IGHV3-23 (immunoglobulin heavy variable 3-23)
Description:
V region of the variable domain of immunoglobulin heavy chains that participates in the antigen recognition. Immunoglobulins, also known as antibodies, are membrane-bound or secreted glycoproteins produced by B lymphocytes. In the recognition phase of humoral immunity, the membrane-bound immunoglobulins serve as receptors which, upon binding of a specific antigen, trigger the clonal expansion and differentiation of B lymphocytes into immunoglobulins-secreting plasma cells. Secreted immunoglobulins mediate the effector phase of humoral immunity, which results in the elimination of bound antigens. The antigen binding site is formed by the variable domain of one heavy chain, together with that of its associated light chain. Thus, each immunoglobulin has two antigen binding sites with remarkable affinity for a particular antigen. The variable domains are assembled by a process called V-(D)-J rearrangement and can then be subjected to somatic hypermutations which, after exposure to antigen and selection, allow affinity maturation for a particular antigen.
Synonyms: DP47; IGHV323; V3-23; VH26
Tractability: Antibody: its Gene Ontology location is reachable by antibodies, with high confidence; UniProt places it where antibodies can reach, with medium confidence; UniProt predicts a signal peptide or a membrane-spanning region.
Gene: Immunoglobulin variable (V) gene on chromosome 14 (106,268,606 to 106,269,140, reverse strand). Ensembl gene ENSG00000211949.
Subcellular location: Secreted; Cell membrane
Pathways (Reactome):
Immune System: Antigen activates B Cell Receptor (BCR) leading to generation of second messengers; CD22 mediated BCR regulation; Classical antibody-mediated complement activation; FCERI mediated Ca+2 mobilization; FCERI mediated MAPK activation; FCERI mediated NF-kB activation; FCGR activation; Fc epsilon receptor (FCERI) signaling; Immunoregulatory interactions between a Lymphoid and a non-Lymphoid cell; Initial triggering of complement; Regulation of Complement cascade; Regulation of actin dynamics for phagocytic cup formation; Role of LAT2/NTAL/LAB on calcium mobilization; Role of phospholipids in phagocytosis
Disease: FCGR3A-mediated IL10 synthesis; FCGR3A-mediated phagocytosis; Potential therapeutics for SARS
Hemostasis: Cell surface interactions at the vascular wall
Vesicle-mediated transport: Scavenging of heme from plasma
Gene Ontology:
Molecular function: antigen binding
Biological process: immune response; immunoglobulin mediated immune response
Cellular component: blood microparticle; extracellular exosome; extracellular region; plasma membrane
Homologues: Paralogues in human: IGHV3-64 (91% identical), IGHV3-66 (91% identical), IGHV3-64D (91% identical), IGHV3-53 (90% identical), IGHV3-74 (90% identical), IGHV3-43 (89% identical), IGHV3-48 (88% identical), IGHV3OR16-10 (88% identical), IGHV3-30 (87% identical), IGHV3-11 (86% identical), IGHV3-21 (86% identical), IGHV3-7 (86% identical), and 65 more.
Diseases named in the same sentence as IGHV3-23 in open-access papers:
IGHV3-23 is named in the same sentence as 4 diseases in open-access papers, as found by Europe PMC text mining. Sharing a sentence is not in itself a finding about the gene and the disease. The quoted sentences say what the papers report.
pneumonia (1 paper, 2019). An acute, acute and chronic, or chronic inflammation focally or diffusely affecting the lung parenchyma, caused by an infection in one or both of the lungs (by bacteria, viruses, fungi, or mycoplasma.). "Moreover, the expression of eight DEPs (PECAM1, PGLYRP1, AHCY, BHMT, EML3, ICOSLG, IGHV3‐23 and RTN4RL2) in normal and pneumonia groups (two patients) was quite different from that in the KD group." (PMID 30761252, 2019). "Moreover, the expression of eight of these 30 DEPs (PECAM1, PGLYRP1, AHCY, BHMT, EML3, ICOSLG, IGHV3‐23 and RTN4RL2) clustered normal and pneumonia samples into one group and clustered KD samples into another group, which heightens the importance of these eight DEPs in KD." (PMID 30761252, 2019).
kidney diseases (1 paper, 2024). "Proteins involved in the regulation of complement cascade (IGKV2-29 and IGHV3-23) and upregulated in the IR group aggravate AKI and its advancement to various kidney diseases." (PMID 39219798, 2024).
IGHV3-23 also shares sentences with these, for which no sentence is quoted: neurological disorders (1 paper); tumor (1).